NTF4 (neurotrophin 4)
Diseases named in the same sentence as NTF4 in open-access papers (continued):
Sharing a sentence is not in itself a finding about the gene and the disease.
colon cancer (1 paper, 2019). "Further studies are still needed to explore the biological functions and underlying molecular mechanisms of REG1B, TGM6, NTF4, PNMA5, and HOXC13 in colon cancer." (PMID 30884206, 2019). "The prognostic signature based on REG1B, TGM6, NTF4, PNMA5, and HOXC13 could divide colon cancer patients into high–risk and low–risk groups, with an AUC of the ROC of 0.771." (PMID 30884206, 2019). "Using these data, we constructed a prognostic signature based on the expression of REG1B, TGM6, NTF4, PNMA5, and HOXC13 which could provide great significant prognostic value for colon cancer." (PMID 30884206, 2019). "We then constructed a prognostic signature based on the expression of REG1B, TGM6, NTF4, PNMA5, and HOXC13 which could provide significant prognostic value for colon cancer." (PMID 30884206, 2019).
hepatocellular carcinoma (1 paper, 2024). A malignant tumor that arises from hepatocytes. "The researchers screened CAR-T cells for brain-derived neurotrophic factor (BDNF) and neurotrophin 4 (NTF4) ligands, and then used a mouse model to create a tumor model by subcutaneously injecting SMMC7721 cells from a human hepatocellular carcinoma cell line." (PMID 38919533, 2024).
Infertility (1 paper, 2020). "The NTRK2 gene encodes the NTRK2 receptor for neurotrophin-4/5 and brain-derived neurotrophic factor leading to oocyte death in late adolescence, loss of follicular tissue and infertility in early adulthood." (PMID 32252625, 2020).
injury (1 paper, 2016). Damage inflicted on the body as the direct or indirect result of an external force, with or without disruption of structural continuity. "Trophic factors, such as brain derived neurotrophic factor and neurotrophin 4/5, are known to improve RGC survival but only partially protect these cells from death after nerve injury." (PMID 27007653, 2016).
insomnia (1 paper, 2024). A sleep disorder characterized by difficulty in falling asleep and/or remaining asleep. "Moreover, it is noteworthy that among genomic factors, only the expression of NTF4 and NTF3 genes in the healthy control group were predictive of insomnia severity and the onset of clinically significant disease, respectively." (PMID 39126038, 2024). "The neurobiological underpinnings of both OSA and insomnia involve complex interactions among various neuromodulators, including brain-derived neurotrophic factor (BDNF), its precursor proBDNF, glial-cell-line-derived neurotrophic factor (GDNF), neurotrophin-3 (NTF3), and neurotrophin-4 (NTF4)." (PMID 39126038, 2024).
memory impairment (1 paper, 2025). "In conclusion, studies show that the upregulation of specific genes and neuronal proteins, including Arc, BDNF (Brain-Derived Neurotrophic Factor), and NT4 (Neurotrophin-4), can limit the progression of memory impairment in diabetic mice." (PMID 38860903, 2025).
metastatic tumors (1 paper, 2023). "The HE staining results of lung metastatic tumors showed that compared with vector-group, the lung metastatic tumors in NTF4-group were smaller in size and more in number." (PMID 36632451, 2023).
Nonsmall-Cell Lung Cancer (1 paper, 2022). "This study aims to uncover the biological function of neurotrophin-4 (NTF4) in affecting the progression of nonsmall-cell lung cancer (NSCLC)." (PMID 36034210, 2022).
oligodendroglioma (1 paper, 2024). A well-differentiated (WHO grade II), diffusely infiltrating neuroglial tumor, typically located in the cerebral hemispheres. "This could be related to the fact that 1p-19q co-deletion in oligodendroglioma involves genes encoding the essential proteins in the formation of TMs, including TTYH1, neurotropic growth factor (NGF), and neurotrophin 4 (NT4), which promotes GAP43 expression." (PMID 38473812, 2024).
proliferative diabetic retinopathy (1 paper, 2013). Advanced retinopathy due to diabetes mellitus characterized by the formation of new vessels in the retina. "We investigated the expression of the NTs nerve growth factor (NGF), brain-derived neurotrophic factor (BDNF), neurotrophin-3 (NT-3), and neurotrophin-4 (NT-4) and their receptors TrkA, TrkB, and TrkC in proliferative diabetic retinopathy (PDR)." (PMID 23762379, 2013).
cancer (22 papers, 2012 to 2025). A tumor composed of atypical neoplastic, often pleomorphic cells that invade other tissues. "A previous study showed that nerve growth factor (NGF) family members such as NGF, neurotrophin-3, and neurotrophin-4/5, which are other ligands of TrkB, influence cancer proliferation." (PMID 28423707, 2017). "Furthermore, it has been seen that IGFBP-2 may regulate the expression of several potential cancer-promoting cytokines including fibroblast growth factors 6 and 7 (FGF-6 and -7), neurotrophin-4 (NT-4), and placental growth factor (PIGF)." (PMID 22927847, 2012).
tumor (16 papers, 2015 to 2025). "Tumor xenografts of cells expressing NTF4 exhibited frequent cytoplasmic fragmentation as well as decreased Ki-67 staining." (PMID 36632451, 2023). "We plan to perform tumor formation experiments in nude mice to explore the role of NTF4 in the tumor growth of NSCLC in the future." (PMID 36034210, 2022). "With primary tumor progress to invasion and metastasis, NTF4 expression increases through an unknown mechanism that allows tumor cells to undergo EMT, invasion and metastasis." (PMID 36632451, 2023). "Based on those investigations, we hypothesized a role for NTF4 in the inhibition of primary tumor colonies by decreasing tumor cell viability and growth at an early stage of tumorigenesis, which may lead to the smaller tumor volume observed in clinic, presenting a “false impression of early tumor”." (PMID 36632451, 2023). "In addition, NTF4 variation impairs TrkB signaling, thus affecting the growth of tumor cells." (PMID 36034210, 2022). "Therefore, it is believed that NTF4 variation is of significance in the tumor process." (PMID 36034210, 2022). "The group with the highest levels of NTF4 tumor expression had poorer OS and DMFS compared to the group with the least NTF4 expression." (PMID 36632451, 2023). "However, when tumors progress, NTF4 promotes EMT and invasion and metastasis of tumor cells." (PMID 36632451, 2023).
genetic disorder (1 paper, 2010). "This, with the added rarity of NTF4 mutations supports the case that POAG is more a complex genetic disorder, with mutations within single genes contributing only a small fraction toward its etiology." (PMID 20806036, 2010).
mental illnesses (1 paper, 2025). "Associated with various mental illnesses, neurotrophins are the most studied subgroup of neurotrophic factors, a family including the nerve growth factor NGF, the brain-derived neurotrophic factor (BDNF), neurotrophin 3 (NT3) and neurotrophin 4 (NT4)." (PMID 40869374, 2025).
NTF4 also shares sentences with these, for which no sentence is quoted: Cerebral ischemia (5 papers); diabetes (5); neurodegenerative disease (5); Alzheimer disease (4); endometriosis (4); primary open-angle glaucoma (4); colon adenocarcinoma (3); mood disorder (3); multiple sclerosis (3); Obesity (3); amyotrophic lateral sclerosis (2); bipolar disorder (2); bladder cancer (2); brain injury (2); cerebral artery occlusion (2); cognitive decline (2); cognitive disorder (2); diabetic retinopathy (2); glioma (2); Huntington disease (2); ischemia (2); melanoma (2); pancreas adenocarcinoma (2); prostate carcinoma (2); schizophrenia (2); Stroke (2); acanthamoebiasis (1); alcoholism (1); allergic asthma (1); allergic rhinitis (1).
A further 46 diseases each share a sentence with NTF4 in 1 paper.